CKS1B (CDC28 protein kinase regulatory subunit 1B)
Diseases named in the same sentence as CKS1B in open-access papers (continued):
Sharing a sentence is not in itself a finding about the gene and the disease.
cancer (continued). "CKS1B is overexpressed in several cancers and binds to cdk2, overcoming the replicative barrier imposed by activated oncoproteins." (PMID 25477524, 2015). "Of particular interest was the drug resistance oncogene CKS1B, which has low-level copy gains (one to three copies) in several cancers." (PMID 25995187, 2015). "The human CKS1B gene is located in a region of chromosome 1q that is frequently amplified in cancer." (PMID 22624029, 2012). "Genetic alterations in key components of these pathways, such as EGFR, BRAF, KRAS, PIK3CA, and PTEN, have been well-documented in NSCLC, and our study suggests that CKS1B may play a role in modulating these alterations to drive cancer progression." (PMID 40165937, 2025). "This highlights the importance of comprehensive studies that consider these variables, as CKS1B overexpression may serve as a marker of cancer progression." (PMID 40165937, 2025). "In addition, overexpression of c-Fos in NQO1-deficient cancer cells suppressed CDK1 kinase activity, an effect that was enhanced by knockdown of CKS1B." (PMID 36793872, 2023). "To establish whether NQO1 regulates AP-1-mediated CKS1 expression in cancer cells, we analyzed the CKS1B promoter, which contains two AP-1-like elements, using a promoter deletion assay and a reporter plasmid." (PMID 36793872, 2023). "Generally, the CKS1B/STAT3 axis contributes to the development of cancer." (PMID 36405738, 2022). "Several researches have illustrated that CKS1B performs a function in cancer progression." (PMID 36405738, 2022). "Thus, previous studies have confirmed that CKS1B plays a vital role in the cancer cell growth, invasion, metastasis and chemical resistance." (PMID 36405738, 2022). "Role of CKS1B in cancer development has been reported in several studies." (PMID 32960462, 2021). "In conclusion, our first pan-cancer analysis of CKS1B contributes to a better overall understanding of CKS1B and may provide a new target for future cancer therapy." (PMID 34845438, 2021). "Generally, CKS1B/STAT3 axis accounts for cancer development." (PMID 32960462, 2021). "CKS1B is reported as a cancer promoter; however, its role in PTC is rarely noticed." (PMID 32960462, 2021). "CKS1B was also reported as a potential target to improve cancer therapy." (PMID 34650921, 2021). "In addition, a meta-analysis including 2,224 cancer participants showed that high CKS1B expression is associated with advanced T stage and lymph node metastasis." (PMID 36405738, 2022). "Therefore, CKS1B is generally regarded as a cancer-promoting factor." (PMID 34845438, 2021). "siRNA-mediated knockdown of c-Fos in NQO1-expressing cancer cells increased CDK1 kinase activity, whereas overexpression of CKS1B decreased c-Fos-mediated enhancement of CDK1 kinase activity in these cells." (PMID 36793872, 2023). "CKS1B(CDC28 protein kinase regulatory subunit 1B)has been reported overexpressed in breast cancer, lung cancer and other malignant tumors due to the amplification of chromosome 1q21(2012)." (PMID 34408811, 2021). "In addition, considering the positive application of cyclin-dependent kinase inhibitor proteins (CDKI) targeting downstream molecule of CKS1B in malignant tumors, profound study of CKS1B might also provide a scientific basis for selecting specific drug targets." (PMID 34925510, 2021). "Overexpression of CKS1B and CKS2 has been documented in a variety of cancers, downstream of a variety of oncogenes, and their high expression has been correlated with poor prognosis." (PMID 28939057, 2018). "Overexpression of CKS1B and CKS2 is observed in multiple human cancers, including various MLL-rearranged (MLLr) AML subtypes." (PMID 28939057, 2018). "We further demonstrated that a novel signaling pathway, the miR-197/CKS1B/STAT3 axis, has the ability to promote cancer progression in chemoresistant NSCLC." (PMID 25597412, 2015).
cancer (continued). "In conclusion, we have identified a novel signaling network, the miR-197/CKS1B/STAT3 axis, which regulates cancer progression in chemoresistant NSCLC." (PMID 25597412, 2015). "In addition, the TIMER analysis revealed that CKS1B was overexpressed in both LUAD and LUSC as compared to other cancer forms." (PMID 40165937, 2025). "The immunohistochemical analysis, enhanced by computer-aided systems and digital imaging, revealed robust nuclear immunoreactivity for CKS1B in LUAD and LUSC tissues, with significantly more intense staining observed in cancer cells compared to normal alveolar cells." (PMID 40165937, 2025). "In view of the finding that CKS1B is upregulated by NQO1 in cancer cells, we hypothesized that NQO1 promotes CKS1B expression in cancer cells through regulation of a transcription factor." (PMID 36793872, 2023). "In the present study, we observed that CKS1B could also positively regulate STAT3/PD‐L1 signaling in PTC cells, and the inhibition of CKS1B could suppress cancer development of PTC by regulating STAT3/PD‐L1 signaling." (PMID 32960462, 2021). "Notably, CKS1B is a CKS family protein that regulates cell cycle progression, growth, apoptosis, invasion metastasis, and chemical resistance in a range of cancer types." (PMID 34568067, 2021). "Moreover, CKS1B and CKS2 are frequently overexpressed in various cancers, including multiple myeloma and breast cancer, correlating with increased proliferation and poor prognosis." (PMID 28939057, 2018). "Furthermore, many genes in cancer-related pathways were also over-expressed in high CIN samples including proliferation (ASPM, CKS1B, MCM gene family, TOP2A, TTK, TYMS) and cancer testis antigens (MAGE family)." (PMID 23840451, 2013). "However, most studies of CKS1B have focused on a single disease, and pan-cancer analysis of it from a holistic perspective has not been reported yet." (PMID 34845438, 2021). "CKS1B has been shown to overcome the DNA damage response barrier triggered by activated oncoproteins, suggesting that in the context of activated MYC its expression could enhance cancer cell fitness." (PMID 25477524, 2015). "Interestingly, we observed a negative correlation between CKS1B expression and DNA methylation of CpG islands in gene promoters, a finding consistent with previous studies linking promoter methylation to transcriptional silencing in various cancer types, including LC." (PMID 40165937, 2025). "Targeting of GMPS, CKS1B, and RAD21 by 2 individual siRNAs attenuated colony-formation potential of cancer cells, while depletion of RAD54L failed to exhibit any effect on colony formation." (PMID 36201246, 2022).
CKS1B also shares sentences with these, for which no sentence is quoted: ovarian carcinoma (4 papers); hepatocellular carcinoma (3); lung adenocarcinoma (3); Burkitt lymphoma (2); cholangiocarcinoma (2); esophageal cancer (2); lung squamous cell carcinoma (2); papillary thyroid carcinoma (2); small cell lung carcinoma (2); acute pancreatitis (1); adenomyosis (1); angiosarcoma (1); bladder cancer (1); bladder urothelial carcinoma (1); breast invasive carcinoma (1); chronic pancreatitis (1); colon adenocarcinoma (1); COVID-19 (1); diffuse large B-cell lymphoma (1); follicular lymphoma (1); gastrointestinal disease (1); gynecologic cancers (1); hematological malignancies (1); infection (1); kidney chromophobe (1); mantle cell lymphoma (1); melanoma (1); monoclonal gammopathy of undetermined significance (1); nonseminomatous germ cell tumors (1); ocular melanoma (1).
A further 11 diseases each share a sentence with CKS1B in 1 paper.